TREM2 (triggering receptor expressed on myeloid cells 2)
Diseases named in the same sentence as TREM2 in open-access papers (continued):
Sharing a sentence is not in itself a finding about the gene and the disease.
demyelination (8 papers, 2017 to 2025). "Trem2 deficiency during viral-induced demyelination dysregulates expression of other select genes regulating phagocytic pathways and lipid metabolism, with distinct effects on microglia and BMDM." (PMID 36333761, 2022). "We, therefore, investigated the role of Trem2 in a viral encephalomyelitis model associated with prominent Th1 mediated antiviral immunity leading to demyelination." (PMID 36333761, 2022). "In CPZ-induced demyelination we further validated previous findings that loss of TREM2 reduces myelin clearance and we showed that loss of one copy of TREM2 has an intermediate phenotype, suggesting that myelin removal by microglia is sensitive to TREM2 copy numbers." (PMID 32772264, 2020). "In a murine model of CNS demyelination, antibody-dependent TREM-2 activation in microglia promoted the clearance of myelin debris, thus enhancing remyelination and axonal integrity." (PMID 35723306, 2022). "Here, we explored the effect of antibody-mediated TREM2 activation on microglia in a well-established toxin-induced model of demyelination in the CNS resulting from exposure to the copper chelator cuprizone (CPZ) in the diet." (PMID 32772264, 2020). "Treatment with a new TREM2 agonistic antibody promoted the clearance of myelin debris in the cuprizone model of CNS demyelination." (PMID 32772264, 2020). "The triggering receptor expressed on myeloid cells 2 (TREM2) plays a pivotal role in this process, enhancing microglial phagocytic activity and degradation of myelin remnants, thereby facilitating neuroprotection in NMOSD-associated demyelination." (PMID 41156105, 2025). "Trem2 deficiency did not alter disease onset or severity, but impaired clinical recovery after onset of demyelination." (PMID 36333761, 2022). "However, TREM2-modulated phagocytic functions are essential for removal of myelin debris and remyelination implicating repair-promoting functions of microglia in the specific tissue environments defining these two demyelination models." (PMID 29942315, 2018). "Although Trem2 ablation did not affect lesion size, sustained accumulation of damaged myelin was consistent with findings in toxin and autoimmune-induced demyelination models." (PMID 36333761, 2022).
Hypertension (8 papers, 2019 to 2025). The presence of chronic increased pressure in the systemic arterial system. "Hypertension and Pb exposure seemed to cause a decrease in the areas of cells with co-location of TREM2 and Iba1, and hypertensive mice with Pb exposure showed less than that of hypertensive mice or Pb-exposed mice." (PMID 39853035, 2025). "ADAM10 or ADAM17, the enzymes cleaving TREM2, were detected to elucidate the mechanism of TREM2 decrease in mice with hypertension, Pb alone, or co-exposure." (PMID 39853035, 2025). "Collectively, the results exhibited that ADAM17 is a major proteolytic enzyme of TREM2 regarding Pb and AngII (hypertension) treatment." (PMID 39853035, 2025). "For instance, upregulated ADAM17 activity reduced TREM2 expression and exacerbated neuroinflammation in a lead exposure‐induced hypertension mouse model." (PMID 41476737, 2025). "Recently, in a mouse model of HFpEF driven by hypertension, Trem2-expressing macrophages were found to be protective in cardiac remodeling." (PMID 40083551, 2025). "Models of hypertension increased the number of activated microglia in the cortex and hippocampus of mice, upregulated triggering receptor expressed on myeloid cells 2 (TREM2) produced by microglia, and increased amyloid-beta deposition." (PMID 36836686, 2023). "In this study, we confirmed for the first time that microglial TREM2 was upregulated in the hypertension group." (PMID 34489683, 2021). "Does TREM2 participate in the regulation of hypertension-induced cerebral microcirculation dysfunctions, or blood pressure?" (PMID 34489683, 2021). "We found that hypertension upregulated TREM2 expression and A1 astrocytes in middle-aged mice for the first time." (PMID 34489683, 2021). "More importantly, microglial TREM2 upregulation was identified in middle-aged mice with hypertension." (PMID 34489683, 2021). "We introduced angiotensin II-induced hypertension in middle-aged mice and found that hypertension-upregulated TREM2 expression and A1 astrocytic activation were involved in neuroinflammation in the animal models used in this study." (PMID 34489683, 2021). "All findings indicated ADAM17 might be a main proteolytic enzyme regarding the TREM2 decrease induced by Pb and AngII (hypertension) exposure." (PMID 39853035, 2025). "Our findings provided new insights into the complex interplay between hypertension, Pb exposure, and neuroinflammation as well as highlight the potential role of TREM2, ADAM17, and miR-26a-5p as therapeutic targets for neuroinflammation in hypertensive populations with Pb exposure." (PMID 39853035, 2025). "Next, to further elucidate whether ADAM10 or ADAM17 were mainly involved in the proteolytic shedding of TREM2 following hypertension and Pb exposure, we examined the protein expressions of ADAM10 and ADAM17 in vivo." (PMID 39853035, 2025). "Notably, hypertensive mice with Pb exposure had a lower expression of the TREM2 protein compared to the mice of hypertension or Pb alone from 4 w exposure and seemingly decreased significantly at 12 w exposure in which the protein expression of TREM2 was 38.4% that of control group." (PMID 39853035, 2025). "TREM2 KO hypertensive mice with Pb exposure exhibited further upregulated proinflammatory cytokines (IL-6, TNF-α) and downregulated anti-inflammatory comparing with C57 mice in the Pb + hypertension group." (PMID 39853035, 2025). "The results in vivo showed that the expression of TREM2 protein of the PFC in hypertensive mice after Pb exposure decreased at 4 w exposure, while the expression of the TREM2 protein in the hippocampus and hypothalamus decreased at 8 w, with both of them only exerted in the Pb + hypertension group." (PMID 39853035, 2025).
liver disease (8 papers, 2019 to 2024). "TREM1 and TREM2 participate in inflammation, metabolism, fibrosis, and tumorigenesis—all of which are closely associated with liver diseases." (PMID 33297569, 2020). "An earlier study demonstrated increased expression of Trem-2 in patients with cirrhotic livers and an association with hepatic injury and inflammatory markers suggesting that Trem-2 functions at counteracting inflammatory events in liver disease." (PMID 37736102, 2023). "The consistent upregulation of Trem2, Anxa2, Ttc39a, and Gdf15 across all stages of liver disease—from steatosis and NASH to fibrosis—suggests that these genes play a pivotal role in the progression of NAFLD." (PMID 39697329, 2024). "Previous studies have highlighted the potential role of TREM2 in the development and progression of liver diseases." (PMID 37430471, 2023). "Here, we review the function of TREM1 and TREM2 in different liver diseases based on inflammation, providing a more comprehensive perspective for the treatment of liver-related diseases." (PMID 33297569, 2020).
metabolic syndrome (8 papers, 2018 to 2025). A cluster of metabolic risk factors for CARDIOVASCULAR DISEASES and TYPE 2 DIABETES MELLITUS. "TREM2, metabolic syndrome, YKL-40, LW-AFC, and lipopolysaccharide are all related to T cells, while YKL-40 and LW-AFC are also associated with gut microbiota." (PMID 40791247, 2025). "The relevance of metabolic syndrome, T cells, and TREM2 remains strong." (PMID 40791247, 2025). "Similarly to PGRN and TDP-43, the metabolic functions of TREM2 seem to contribute to ALS: TREM2 deficiency is deleterious in ALS, whereas TREM2 over-expression leads to various features of metabolic syndrome that have been shown to be favorable in ALS." (PMID 30509290, 2018).
periodontitis (8 papers, 2022 to 2025). An acute or chronic inflammatory process that affects the tissues that surround and support the teeth. "Taking NF-κB as an example, Trem2 played a significant promotive role in regulating the intracellular ROS level, NF-kB phosphorylation, and nuclear translocation in periodontitis-activated osteoclasts." (PMID 37212865, 2023). "Previous research has shown that triggering receptors expressed on myeloid cells 2 (Trem2) regulates osteoclast differentiation with impaired bone resorption capability in the periodontitis environment." (PMID 35185928, 2022). "This study also found that the TREM2-dependent cascade was a significant signaling pathway of ROS-mediated osteoclastogenesis, suggesting that the TREM2-mediated ROS signal amplification cascade is essential in periodontitis osteoclastogenesis." (PMID 41048977, 2025). "Shared genetic risk factors between periodontitis and Alzheimer’s have also been proposed, such as polymorphisms in genes related to innate immunity and inflammatory response (e.g., TLR4, NLRP3, TREM2)." (PMID 40231144, 2025). "In a mouse model of periodontitis, knockout of TREM2 results in reduced bone invasion." (PMID 39865310, 2025). "Additionally, studies have demonstrated that in the alveolar bone of individuals with chronic periodontitis, there is a significant upregulation of TREM2 expression." (PMID 39865310, 2025). "Triggering receptors expressed on myeloid cells 2 (Trem2) could regulate osteoclast differentiation via intercellular ROS signals during periodontitis." (PMID 35185928, 2022).
steatosis (8 papers, 2019 to 2024). Increased lipid within the cytoplasm of cells. "Interestingly, the prevalence of these TREM2-positive macrophages also known as NAM is strongly associated with the severity of steatosis, inflammation, hepatocyte ballooning, and fibrosis." (PMID 35874657, 2022). "Foz/Foz mice and Foz::Trem2−/− had equivalent steatosis and fibrosis when the mice continued on WD till 20 wk, since the disease phenotype catches up by this time (as discussed in SI Appendix)." (PMID 39172787, 2024). "We also analyzed the expression levels of Trem2, Anxa2, Ttc39a, and Gdf15 across various stages of the disease, including steatosis, NASH, and fibrosis." (PMID 39697329, 2024). "Further, when fed a HFD, Trem2−/− mice had increased liver triglyceride levels, suggesting hepatic steatosis as also visible in H&E-stained liver sections." (PMID 36766683, 2023). "In particular, as recently reported, SerpinB3 was able to influence the hepatic levels of Galectin 3, CD9 and TREM2, typical markers of NAMs, a population of hepatic macrophages emerging in progressive NAFLD-NASH and strictly associated with severity of steatosis, inflammation as well as fibrosis." (PMID 38307387, 2024). "However, recent reports indicate that the TREM2 molecule itself plays a protective role in liver damage, steatosis, and MASH." (PMID 39172787, 2024). "Although TREM2 has been shown to be up-regulated in advanced MASH livers, at what stage TREM2 is induced during the disease progression and what event (such as steatosis, fibrosis, or hepatocyte death) triggers TREM2 upregulation are not clear." (PMID 39172787, 2024). "The analysis of genes identified in NAFL-Steatosis patients and NAFL-NASH patients (n = 58 genes) and in NASH patients (n = 141 genes) with high MMP9 level showed that 4 genes, FABP4, MMP9, HELLS and TREM2, were shared between these three groups of patients." (PMID 31874999, 2019). "Compared with their Sham controls, VSG failed to decrease the liver weight, hepatic steatosis, ALT, and AST in TREM2 KO mice, suggesting that TREM2 is required for the VSG-induced reversal of MASH." (PMID 37961666, 2023).
age-related macular degeneration (7 papers, 2016 to 2026). Age-related loss of vision in the central portion of the retina (macula), secondary to retinal degeneration. "Using retina samples, they confirmed that expression of miR-34a was higher in those obtained from patients with age-related macular degeneration (AMD), whereas TREM2 expression was lower." (PMID 35563685, 2022).
autoimmune disease (7 papers, 2014 to 2024). A disorder resulting from loss of function or tissue destruction of an organ or multiple organs, arising from humoral or cellular immune responses of the individual to their own tissue constituents. "Variations in TREM2 are implicated in autoimmunity and increased risk of autoimmune disease." (PMID 34539672, 2021). "Based on the regulation of the IFNAR1 pathway by TREM2, we hypothesize that TREM2 modulation may serve as a therapeutic modality for autoimmune diseases." (PMID 38956653, 2024). "Thus, the function of TREM2+ cells may differ based on organ/disease context, with evidence that these cells promote progression of some autoimmune diseases." (PMID 39867899, 2024). "It is tempting to speculate that targeting the TREM-2 pathway could be used as a novel strategy for modulating C1q production and pulmonary innate immune responses, which might be of relevance to other respiratory tract infections and possibly autoimmune diseases." (PMID 24945405, 2014). "Notably, both HLA-I-specific and HLA-II-specific pGenes included known drug targets for autoimmune diseases, infectious diseases, and cancer such as LAG3, PDCD1, TNF, and ACE2 affected by HLA-I; and IL18, TREM2, VSIG4, and TLR1 by HLA-II." (PMID 39085222, 2024).
brain injury (7 papers, 2015 to 2025). Acute and chronic (see also brain INJURIES, CHRONIC) injuries to the brain, including the cerebral hemispheres, CEREBELLUM, and brain STEM. "Knockdown of TREM2 in primary microglia leads to a reduction in cell number and TREM2 deficiency inhibits myeloid cell population growth in response to traumatic brain injury and aging." (PMID 30587772, 2018). "The unexpected increase in both myelin and lipid accumulation observed in Cd36 and Trem2 deficient microglia and monocytes following brain trauma may reflect redundancy and compensatory mechanisms among scavenger receptors." (PMID 40964307, 2025). "A particular challenge is to potentially interfere with adult brain plasticity processes to improve cognitive performance by using Gal-3 as an endogenous modulator of neuroinflammation/neurodegeneration and ligand for TLR and TREM2 as key receptors in microglial activation and brain trauma." (PMID 35875353, 2022).
colon carcinoma (7 papers, 2019 to 2025). "However, the underlying mechanisms by which TREM2 regulates Wnt signaling in colon cancer cells are completely unknown." (PMID 31489935, 2019). "Examining the correlation between elevated TREM2 expression and clinical outcomes, we stratified colon cancer cases into TREM2high and TREM2low groups and plotted prognosis curves in Kaplan-Meier Plotter." (PMID 39744236, 2025). "To explore the role of TREM2 in colon cancer development, we conducted a human colon carcinoma and normal tissue array containing 110 human core colon cancer tissues and 10 normal tissues." (PMID 31489935, 2019). "Surprisingly, our results demonstrated that early-stage colon cancer tissues were characterized by high TREM2 protein levels compared with normal colon tissues." (PMID 31489935, 2019). "To explore the effect of TREM2 on the metastatic potential of colon cancer cells, we performed scratch wound healing and Matrigel invasion assays." (PMID 31489935, 2019). "To identify the physiological relationship between TREM2 and human colon cancer, we conducted a human colon cancer tissue array using a TREM2-specific antibody." (PMID 31489935, 2019). "In this study, we demonstrated that TREM2 inhibits the proliferation of colon cancer cells by attenuating cell cycle progression by downregulating cyclin D1 expression." (PMID 31489935, 2019). "We therefore investigated the molecular mechanism by which TREM2 regulates the Wnt/β-catenin signaling pathway in HT29 colon cancer cells." (PMID 31489935, 2019). "Consist with the decreased proportion of M2 macrophages, the CD206 expression in tumor by immunostaining and the mRNA levels of representative M2 genes (Arginase1, CD206, Trem2 and Ym1) by qPCR were also markedly down-regulated in colonic tumors of H. pylori-infected CAC mice." (PMID 33201893, 2020). "According to pathological T-stage classification, we found that although TREM2 protein levels were heterogeneous in T3- and T4-stage samples, TREM2 levels in intensity 1 group were increased to 40%, 49% and 63% in T2-, T3- and T4-stage human colon carcinoma tissues, respectively." (PMID 31489935, 2019). "Phosphorylation of GSK-3β at Ser9 and total β-catenin levels suggested that the suppression of EpCAM might be due to alterations in the TREM2-mediated Wnt/β-catenin signaling pathway and that TREM2 might be involved in the tumorigenicity of colon cancer." (PMID 31489935, 2019). "Furthermore, stage II and stage III colon cancer tissues harbored TREM2 protein levels that were approximately 25–33% higher than those in normal colon tissues." (PMID 31489935, 2019). "Importantly, the effect of TREM2 in the suppression of tumor development was demonstrated by in vivo and in vitro assays, as well as in human colon cancer patient tissue arrays." (PMID 31489935, 2019). "Therefore, the TREM2-mediated Wnt/ERK/GSK-3β signaling pathway inhibited the metastasis of HT29 colon cancer cells." (PMID 31489935, 2019). "Therefore, we provided the first demonstration that TREM2 is required for the suppression of colon cancer development." (PMID 31489935, 2019). "Importantly, the ability of TREM2 to inhibit the tumorigenicity of colon cancer was further supported by our finding that TREM2 expression in human colon cancer tissues is gradually decreased in a tumor stage-dependent manner." (PMID 31489935, 2019). "Furthermore, the involvement of TREM2 in the pathophysiology of various cancers, especially colon carcinoma, is completely unknown." (PMID 31489935, 2019). "By targeting the inhibitory receptor TREM2 and activating the STING signaling pathway in TAMs, GB2 demonstrates promising therapeutic effects in mouse colon cancer models." (PMID 39744236, 2025). "Results reveal that high TREM2 expression correlates with shorter median refractory free survival (RFS) and overall survival (OS) in colon cancer." (PMID 39744236, 2025).
colon carcinoma (continued). "The tumoricidal effect of the constructs was detected by analyzing cell viability using the CCK8 kit in mouse colon cancer MC38 cells cultured for 24 h with PD-1 scFv, TREM2 scFv, and BsAb." (PMID 37563723, 2023). "We found that normal colon tissues and stage I colon carcinoma contained higher TREM2 protein levels (intensity grades 2 and 3) than stage II, III and IV colon carcinoma, as shown in the representative images." (PMID 31489935, 2019). "Therefore, TREM2 may act as an indicator and/or potential new therapeutic target for colon cancer." (PMID 31489935, 2019). "Importantly, compared with normal colon tissues and human colon carcinoma tissues with stage I, the colon carcinoma tissues with stage II, III and IV expressed lower level of TREM2 protein and this decrease was in a tumor stage-dependent manner." (PMID 34539652, 2021). "In conclusion, our results strongly suggest that TREM2 is highly involved in the malignancy of colon cancer cells but not in the cell transformation stage." (PMID 31489935, 2019). "We found that TREM2 inhibited the canonical Wnt1/β-catenin signaling pathway, which in turn suppressed the proliferation and tumorigenicity of HT29 colon cancer cells by inhibiting β-catenin/TCF4 transactivation activity, resulting in the suppression of cell proliferation and DNA synthesis." (PMID 31489935, 2019). "Furthermore, TREM2 increases β-catenin phosphorylation by activating GSK-3β, which suppresses β-catenin accumulation and TCF4 transcriptional activity, resulting in the downregulation of tumorigenicity in colon cancer cells." (PMID 31489935, 2019). "Furthermore, the gene expression of Wnt and TCF4 was suppressed by the transient expression of TREM2 compared with that in non-transfected or mock-transfected colon cancer cells." (PMID 31489935, 2019).